NEAT1 (nuclear paraspeckle assembly transcript 1)
Diseases named in the same sentence as NEAT1 in open-access papers (continued):
Sharing a sentence is not in itself a finding about the gene and the disease.
gastric cancer (96 papers, 2016 to 2026). A primary or metastatic malignant neoplasm involving the stomach. "Others have reported that overexpression of NEAT1 is corrected with clinical stage, distant metastasis, and prognosis of gastric cancer and knockdown of NEAT1 suppressed EMT-associated protein expression of gastric cancer cell." (PMID 32596382, 2020). "In addition, a link of NEAT1 rs3825071 with the risk of gastric cancer 22 and clinical stage and lymph node metastasis of tongue cancer 23 was recently detected." (PMID 41323778, 2025). "It has been reported that the rs3825071 variant may alter the local folding structures of Neat1 and reduce a binding site for hsa-miR-5092 in gastric cancer patients." (PMID 40027195, 2025). "NEAT1 gene is a hotspot for mutations in some types of cancer, and NEAT1 is overexpressed in the majority of solid tumours, including breast, prostate, lung, colorectal, and gastric cancer." (PMID 36099417, 2022). "Furthermore, lncRNA NEAT1 can act as an excellent diagnostic biomarker of gastric cancer patients for distinguishing the tumor and control samples of Isfahan population." (PMID 35581633, 2022). "Moreover, NEAT1 expression is a novel prognostic and diagnostic biomarker in gastric cancer, colorectal cancer, esophageal squamous cell carcinoma, and prostate cancer." (PMID 33738254, 2021). "Moreover, NEAT1 expression is also a novel prognostic and diagnostic biomarker in gastric cancer, colorectal cancer, esophageal squamous cell carcinoma, and prostate cancer." (PMID 29515109, 2018). "In gastric cancer, hnRNPA2B1 stabilizes lncRNA NEAT1, facilitating CSC properties and chemoresistance via Wnt/β-catenin activation." (PMID 41522354, 2026). "The m6A eraser ALKBH5 binds and demethylates NEAT1 transcript in gastric cancer, increasing NEAT1 activity." (PMID 41301491, 2025). "The m6A eraser ALKBH5 promotes the invasion and metastasis of gastric cancer (GC) by removing the m6A modification on the lncRNA NEAT1." (PMID 38895621, 2024). "The compound demonstrated its antitumor properties in gastric cancer cell lines by interfering with the MAPK signaling cascade through the suppression of the nuclear paraspeckle assembly transcript 1 (NEAT1) protein level." (PMID 37513450, 2023). "From the same analysis comparing sensitive cells in C1 to resistant cells in the remaining clusters, we detected NEAT1 up-regulation, a gene that promotes gastric cancer angiogenesis." (PMID 37917660, 2023). "NEAT1 regulates angiogenesis and promotes gastric cancer progression through upregulation of the miR-17-5p/TGFβR2 axis." (PMID 36506097, 2022). "ROC analysis revealed that NEAT1 can be an excellent prognostic biomarker for the Isfahan gastric cancer patient and can be a novel factor for distinguishing the tumor samples from control samples (AUC: 0.924, p-value < 0.0001)." (PMID 35581633, 2022). "Real-time PCR data analysis revealed that NEAT1 has a significant down-regulation in the Isfahan human gastric cancer samples, compared to control (logFC: -3.775, p-value < 0.0001)." (PMID 35581633, 2022). "Others assessed the correlation between ER stress or cell death and the relative quantity of NEAT1 RNA in gastric cancer tissues." (PMID 35893235, 2022). "NEAT1 is significantly upregulated in human gastric cancer cells, including BGC823, SGC-7901, AGS, MGC803, and MKN28 cells, compared with normal gastric epithelial cells such as GES-1." (PMID 36011001, 2022). "ALKBH5 stimulates gastric cancer’s invasion and metastasis through lowering lncRNA NEAT1’s methylation." (PMID 34476213, 2021). "NEAT1 expression is upregulated in many human malignancies, such as lung, esophageal and gastric cancers." (PMID 35127729, 2021). "LncRNA NEAT1 plays an important role in many diseases, such as gastric cancer, prostate cancer, renal fibrosis, and osteosarcoma." (PMID 33478594, 2021).
gastric cancer (continued). "For instance, lncRNA NEAT1 promotes cell proliferation and migration of gastric cancer, cervical cancer, endometrial cancer and bladder cancer." (PMID 33645623, 2021). "For instance, KLF5-activated lncRNA NEAT1 accelerated gastric cancer progression via serving as a scaffold for BRG1 to down-regulate GADD45A expression." (PMID 33931086, 2021). "Upregulation of NEAT1 or knockdown of miR-1224-5p prompts gastric cancer cell proliferation and migration." (PMID 34147108, 2021). "Long Non-Coding RNA NEAT1 sponges miR-365a-3p to enhance progression of gastric cancer by tarheting ABCC4." (PMID 34789263, 2021). "For instance, m6A demethylase ALKBH5 was reported to induce gastric cancer metastasis by demethylating lncRNA NEAT1, whereas an earlier study showed an important role for ALKBH5 in inhibiting pancreatic cancer progression." (PMID 32218194, 2020). "For instance, the upregulation of the lncRNA NEAT1 in gastric cancer was attributed to a decrease in methylation by the RNA demethylase ALKBH5 (alkylation repair homolog protein 5)." (PMID 33291485, 2020). "Long noncoding RNA nuclear-enriched abundant transcript 1 (NEAT1) exhibits an oncogenic role in multiple cancers, including gastric cancer (GC)." (PMID 33292252, 2020). "Previous studies have shown that NEAT1 silencing suppresses gastric cancer cell migration and invasion in vitro." (PMID 28968960, 2017). "Among these NEAT1-regulated miRNAs, miR- 129- 5p was of particular interest as it was previously reported to be epigenetically silenced in breast and gastric cancers." (PMID 27556296, 2016). "ALKBH5, as an m6A eraser, could inhibit the methylation of lncRNA NEAT1 and further facilitate metastasis and invasion of gastric cancer." (PMID 40069867, 2025). "ALKBH5 (alkylation repair homolog 5) promotes invasive spread of gastric cancer by lowering the methylation of lncRNA NEAT1, and it may be a possible target for therapy." (PMID 38329551, 2024). "Especially in gastric cancer cells, long non-coding RNA NEAT1 could regulate STAMBPL1 expression and promote its malignant behavior." (PMID 38419066, 2024). "Additionally, HULC and NEAT1 contribute to the development of gastric cancer cells' increased ADR resistance." (PMID 38294554, 2024). "Many oncogenic lncRNAs, including nuclear paraspeckle assembly transcript 1 (NEAT1), MALAT1, UCA1, and prostate cancer-associated transcript 1 (PCAT-1), as well as some tumor suppressor lncRNAs, have been shown to play a role in gastric cancer chemoresistance." (PMID 38294554, 2024). "Specifically, NEAT1 can function as a scaffold by interacting with EZH2 to regulate the expression of EZH2 downstream genes, of which dysregulation is associated with invasion and metastasis of gastric cancer cells." (PMID 37365581, 2023). "Other studies showed that ALKBH5 could promote the metastasis and invasion of gastric cancer by demethylating the expression of lncRNA NEAT1 and that METTL14 acts as a prognostic biomarker in colorectal cancer by downregulating oncogenic lncRNA XIST." (PMID 35309906, 2022). "LncRNA NEAT1 acts as contributor of gastric cancer via sponging miR-1224-5p." (PMID 35322746, 2022). "In contrast, Adriamycin inhibits NEAT1 expression in stomach cancer." (PMID 36316461, 2022). "NEAT1 had a significant down-regulation in the gastric cancer samples compared to the control." (PMID 35581633, 2022). "NEAT1/miR-17-5p/TGFβR2 axis promotes gastric cancer progression through up-regulated angiogenesis." (PMID 36523600, 2022). "In gastric cancer, NEAT1 serves as a bad prognostic factor and can promote cancer growth." (PMID 33393590, 2021). "Long non-coding RNAs most often function as competing endogenous RNAs (ceRNAs) to regulate downstream mRNAs by sponging miRNAs, suggesting that NEAT1 may exert its function in gastric cancer in a ceRNA manner." (PMID 34552925, 2021).
gastric cancer (continued). "LncRNA nuclear-rich transcripts 1 (NEAT1) has been found to play an oncogenic role in diverse tumors, such as endometrial cancer, breast cancer, lung cancer, colon cancer and gastric cancer." (PMID 33645623, 2021). "Consistently, through the dual luciferase reporter assay and RNA pull-down assay, we found that the oncogenic function of NEAT1 in gastric cancer was modulated through its interaction with miR-17-5p, which has been identified as an oncogenic miRNA in a variety of tumor types." (PMID 34552925, 2021). "Accumulating evidences have revealed that NEAT1 is dysregulated and acts as an unfavorable prognostic factor in human cancers including gliomas, colorectal cancer, liver cancer, gallbladder cancer, and gastric cancer." (PMID 34552925, 2021). "Besides, ALKBH5 participated in the carcinogenicity of gastric cancer by affecting the methylation of NEAT1." (PMID 32742194, 2020). "In addition, lncRNAs HULC and NEAT1 are also involved in enhancing ADR resistance of gastric cancer cells." (PMID 32192494, 2020). "LncRNA NEAT1 down-regulation was found to restrain the development of gastric cancer and myeloma." (PMID 31868202, 2020). "Given that the miR-129 gene is epigenetically silenced in breast and gastric cancers via DNA methylation, we hypothesized that NEAT1 may regulate the DNA methylation status of the miR-129 gene to modulate its expression." (PMID 27556296, 2016). "To identify the roles and molecular mechanisms of LncRNA NEAT1 in gastric cancer (GC), we analyzed the expression of NEAT1 in GC across the GEO database." (PMID 34552925, 2021). "ALKBH5 favors the invasion and metastasis of gastric cancer (GC) by demethylating lncRNA nuclear paraspeckle assembly transcript 1 (NEAT1)." (PMID 32767982, 2020). "Furthermore, NEAT1 was reported as a decoy of miR-107 in gastric cancer cells." (PMID 32099901, 2020). "Besides, H. Tan found that NEAT1 could modulate miR-506, and thus involved in the gastric cancer development." (PMID 31462890, 2019). "Elevated NEAT1 then acts as a scaffold, influencing the expression of EZH2 and consequently promoting the invasion and metastasis of gastric cancer (GC) cells." (PMID 40384875, 2025). "The NEAT1/miR-130/IRF1 axis in gastric cancer, NEAT1/miR-24-3p/LRG1 axis in thoracic aortic aneurysm, NEAT1/miR-324-5p/RAN axis in retinoblastoma and NEAT1/miR-497-5p/PIK3R1 axis in renal tubular oxidative injury have been widely studied." (PMID 39546499, 2024). "Further detection results demonstrated that both LncRNA NEAT1 and ALKBH5 were overexpressed in gastric cancer cells and tissues." (PMID 37365581, 2023). "Both ALKBH5 and the lncRNA nuclear paraspeckle assembly transcript 1 (NEAT1) were highly expressed in gastric cancer cells and gastric cancer tissues." (PMID 35628623, 2022). "For example, NEAT1 can promote prostate cancer by regulating ACSL4 via sponging miR-34a-5p and miR-204-5p, and promotes the growth of gastric cancer cells by regulating the miR-497-5p/PIK3R1 axis." (PMID 33738254, 2021). "For instance, NEAT1 functions as a sponge for miR-365a-3p to facilitate gastric cancer progression through targeting ABCC4; furthermore, NEAT1 sponges miR-129 to regulate renal fibrosis via modulating coll I." (PMID 34040522, 2021). "High expression levels of lncRNA nuclear paraspeckle assembly transcript (NEAT1) and RSF1 and low expression levels of miR-1224-5p coexist in gastric cancer." (PMID 34147108, 2021). "In fact, NEAT1 was shown to sponge hsa-miR-335-5p, releasing ROCK1 from its suppression, which promotes cell proliferation, migration, and invasion in gastric cancer." (PMID 35008626, 2021). "NEAT1 inhibitors and RSF1 inhibitors have opened up new prospects for the treatment of gastric cancer." (PMID 34147108, 2021). "ALKBH5 decreased the level of lncRNA nuclear paraspeckle assembly transcript 1 (NEAT1), which was overexpressed in gastric cancer cells and tissue, and took a great part in the invasion and metastasis of gastric cancer." (PMID 32742194, 2020).
gastric cancer (continued). "Multiple onco-lncRNAs, such as HOTAIR, CASC9, MRUL, UCA1, D63785, NEAT1 and HULC, are involved in ADR resistance in gastric cancer." (PMID 32192494, 2020). "NEAT1 (nuclear enriched abundant transcript 1) has been shown to promote EMT in nasopharyngeal carcinoma, and gastric cancer." (PMID 28430163, 2017). "Moreover, over-expressed NEAT1 combined with the enhancer of zeste homologue 2 (EZH2) to upregulate the expression of downstream genes of EZH2, thereby promoting gastric cancer invasion and metastasis." (PMID 35628623, 2022). "Finally, a positive correlation between NEAT1 and TGFβR2, VEGF-A, Smad4, PDGFB was seen in GEO gastric cancer datasets GSE62254 (n = 200)." (PMID 34552925, 2021). "LINC00958 promotes aerobic glycolysis of GC cells by enhancing the stability of GLUT1 mRNA; ALKBH5 promotes the high expression of lncRNA NEAT1 in gastric cancer cells and tissues through demethylation." (PMID 35070987, 2021). "The lncRNA NEAT1, in conjunction with hnRNPA2B1, targets RPRD1B mRNA stability, activating the c-Jun/c-Fos/SREBP1 axis to promote fatty acid metabolism and primary tumor lymph node implantation in gastric cancer (GC)." (PMID 37546413, 2023). "Consistent with our findings for dysregulated lncRNAs in SCLC, previous studies found that lncRNAs DLX6-AS1 and NEAT1 were significantly dysregulated in non-SCLC, gastric cancer and pancreatic cancer." (PMID 35860558, 2022).
colorectal cancer (95 papers, 2015 to 2026). A primary or metastatic malignant neoplasm that affects the colon or rectum. "NEAT1 mutations that alter the binding of NEAT1 to miRNAs have been reported in colorectal cancer patients who relapsed after treatment." (PMID 40783798, 2025). "mtr-miR-5754 and gma-miR4995 directly target the tumor-associated long non-coding RNA MALAT1 and NEAT1 and attenuate proliferation of colorectal cancer cells." (PMID 40149445, 2025). "NEAT1 is implicated in the regulation of cell proliferation and migration in colorectal cancer (CRC) through the NEAT1/miR-196a/GDNF pathway." (PMID 39830506, 2024). "NEAT1 exhibited upregulation in both colorectal cancer tissues and cells, and knockdown of NEAT1 inhibited colorectal cancer proliferation and causes decreased ZEB1 expression and increased miR-448 expression." (PMID 39830506, 2024). "Further, we found that NEAT1 expression level is significant high in colorectal cancer and is associated with poor clinical outcome." (PMID 36213831, 2022). "Summarily, we found that NEAT1 expression level is related to colorectal cancer occurrence and progression and is associated with poor clinical outcome." (PMID 36213831, 2022). "By bioinformatics prediction, it is found that NEAT1 expression level is significantly higher in the peripheral blood of patients with colorectal cancer and is associated with poor prognosis." (PMID 36213831, 2022). "In summary, our study suggests that NEAT1 expression is associated with poor prognosis in patients with colorectal cancer." (PMID 36213831, 2022). "In this study, we found that NEAT1 showed an abnormal high expression level in colorectal cancer tissues and cells and is associated with poor prognosis of patients." (PMID 36213831, 2022). "The diagnostic value of NEAT1 was validated in a cohort of colorectal cancer patients, because the whole-blood NEAT1 expression was significantly increased in cancer patients than persons without cancer." (PMID 30374364, 2018). "Our findings indicated the significant promise of whole blood NEAT1 expression as a diagnostic marker in colorectal cancer and thus, warrants confirmation in larger studies." (PMID 26552600, 2015). "Based on the subgroup classification, we next analyzed the association of NEAT1 expression with clinicopathologic characteristics of colorectal cancer patients." (PMID 26314847, 2015). "We evaluated the diagnostic and prognostic value, and origin of whole blood NEAT1 in colorectal cancer." (PMID 26552600, 2015). "In the present study, we determined the diagnostic and prognostic significance and of whole blood NEAT1 in patients with colorectal cancer." (PMID 26552600, 2015). "Whole blood NEAT1 expression is a novel diagnostic and prognostic biomarker of overall survival in colorectal cancer." (PMID 26552600, 2015). "In conclusion, our study established and validated NEAT1 as a new diagnostic biomarker in colorectal cancer." (PMID 26552600, 2015). "This survival pattern indicated that patients with colorectal cancer of high NEAT1 expression had a higher risk of tumor relapse compared with colorectal cancer of low NEAT1 expression." (PMID 26314847, 2015). "The diagnostic value of NEAT1 was validated in a larger, independent cohort of colorectal cancer patients (n = 100) and NCs (n = 100)." (PMID 26552600, 2015). "The expression of both NEAT1 variants was significantly higher in colorectal cancer patients than in NCs (both p < 0.0001)." (PMID 26552600, 2015). "The diagnostic value of whole blood NEAT1 expression was evaluated in test (n = 60) and validation (n = 200) cohorts of colorectal cancer patients and normal controls (NCs)." (PMID 26552600, 2015). "Kaplan-Meier analysis proved that NEAT1 was associated with both disease-free survival and overall survival of patients with colorectal cancer that patients with high NEAT1 expression tend to have unfavorable outcome." (PMID 26314847, 2015).